CD40 (CD40 molecule)
Diseases named in the same sentence as CD40 in open-access papers (continued):
Sharing a sentence is not in itself a finding about the gene and the disease.
COVID-19 (continued). "Early stage COVID-19 patients were enriched for suppressive neutrophil, monocyte, PC, IFN, CD40 activated B cell, cell cycle, and NFkB gene signatures." (PMID 36189236, 2022). "The immune and inflammatory response in the COVID-19 patients, as revealed by the cell-cell communication analysis, is modulated not only by CD22-CD45 interaction, but also CD40 and CD40LG interaction." (PMID 36532041, 2022). "In contrast to T and NK cells, we observed increased evidence of B cell activation through CD40/CD40L and an increased plasma cell signature in the blood of COVID-19 patients." (PMID 33782412, 2021). "The dysregulation of DC function in COVID-19 was also presented by the expression of the maturation marker (CD83), T-cell stimulation molecules (CD40, CD80, CD86) and antigen presentation molecules (HLA-DQA2 and FCER1A)." (PMID 34502134, 2021). "In lung, CD40, CD80, CD83 and HLA-DQA2 were upregulated while CD86 and FCER1A were decreased in mild COVID-19 as compared to healthy controls." (PMID 34502134, 2021). "Our research indicated that certain polymorphisms in the genes ACE2 rs2074192, IFNAR2 rs2236757, OAS1 rs10774671, OAS3 rs10735079, CD40 rs4813003, FCGR2A rs1801274 and CASP3 rs113420705 could predict cytokine responses in pediatric COVID-19 patients." (PMID 40066463, 2025). "Conforming with previous reports, the level of the following markers, CA12, soluble CD40, IL-6, IL-8, soluble PD-L1, and VEGF, were significantly increased by 1.5-fold, 1.5-fold, 6-fold, 2-fold, 2-fold, and 1.5 fold, respectively, in COVID-19 deceased patients compared to control cohort (p ≤ 0.05)." (PMID 36428847, 2022). "To explore whether the monocytes from COVID-19 patients exhibit a similar phenotype, we evaluated the expression levels of several activation markers, including CD33, CD86, CD80, HLA-DR, and CD40, in monocytes isolated from the peripheral blood mononuclear cells (PBMCs) of HD, MP and SP group." (PMID 39996729, 2025). "Comparing 35 non-hospitalized and 11 hospitalized COVID-19 patients revealed that a few signatures were commonly enriched in all COVID-19 patients regardless of disease severity, including PCs, CD40 activated B cells, the alternative complement pathway, and the cell cycle." (PMID 36189236, 2022). "Mild COVID-19 patients displayed a reduced expression of CD40, but not HLA-DR on B cells." (PMID 33692788, 2021). "However, the elevated naïve B cell infiltration, uncorrelated gene-sets of B cell proliferation and differentiation in the cluster of B cell mediated immune response, and the negative enrichment of CD40/CD40L signaling are all specific to the lung tissue of COVID-19 patients." (PMID 33264345, 2020).
viral infection (40 papers, 2010 to 2026). "Here, we investigate the in vivo requirements for CD40 signaling and the associated downstream pathways required for the innate immune control of two distinct murine models of virus infection and disease." (PMID 37376652, 2023). "Given our cell culture findings establishing a critical role for both IFN-γ and Mφ expression of CD40 for protection against acute virus infection, we interrogated whether IL-12 was functionally linked to IFN-γ production and protection in vivo." (PMID 37376652, 2023). "By contrast, the roles of CD40 in regulating innate immune cell activation and function and protection from acute viral infections are less well-characterized." (PMID 37376652, 2023). "These critical circuits are engaged upon virus infection, which supports that CD40 signaling plays a critical role in coordinating innate immune responses." (PMID 37376652, 2023). "NKT cells are known to protect against viral infection and cancer by modulating innate and adaptive immune responses via cytokine secretion, CD40 upregulation, and DC activation." (PMID 30998796, 2019). "Our lab has previously identified that APC expression of CD40 is a mechanism by which viral infection contributes to EAE by diminishing responding regulatory T-cell populations." (PMID 28974943, 2017). "In dendritic cells, the activation of C1qR enhanced the secretion of IFN-γ and the expression of CD40, which both reduced inflammation and combat viral infections." (PMID 29182620, 2017). "We used a peptide/CD40/poly(I:C) vaccination strategy that induces protection against viral infection and promotes tumor eradication." (PMID 26745507, 2016). "The viral infection inhibited the expression of cell maturation surface markers (CD40, CD80 and CD83) and MHCI, and impaired the ability of P3-infected DCs for activating allogeneic naïve T cells." (PMID 21269456, 2011). "Immunophenotyping of lymphocytes and monocytes including quantities of the fractions of HLA-DR expressing T cells and the level of CD40 expression on monocytes can differentiate between acute bacterial and viral infections." (PMID 20626864, 2010). "During viral infections, CD40 binds to CD40L, activating signaling pathways such as the phosphatidylinositol 3-kinase/Akt (PI3K/Akt) and p38 mitogen-activated protein kinase (p38 MAPK), promoting the secretion of pro-inflammatory cytokines to neutralize pathogens." (PMID 39253091, 2024). "Not only are agonists of CD40 increasingly clinically available, but a clearer understanding of the signaling events that occur early during acute viral infection may open up the door towards the development of needed antiviral therapies." (PMID 37376652, 2023). "To build upon these observations and determine if our findings were applicable to a wider array of viral infections, we investigated whether CD40 signaling exerted a similar protective effect within the lung during acute influenza A virus (IAV) infection." (PMID 37376652, 2023). "CD40+ CSF EVPs may be increased in viral diseases since CD40+ cells are commonly activated and increased in the CNS during infection." (PMID 37622115, 2023). "Here, we show the critical role of macrophage CD40 signaling in the control of virus infection and early pathology associated with negative-strand RNA virus infection of mice." (PMID 37376652, 2023). "Similarly, we propose that further examination of CD40 on both T cells and APCs in relation to viral infections in T1D onset is worthwhile." (PMID 28974943, 2017). "Among the sICs, CD27 and CD40, which were identified as factors with high prognostic power through ML analysis in this study, play important roles in promoting the survival and effector functions of natural killer/T cells in viral infection, IFN-I response, and inhibition of its signaling." (PMID 39654974, 2024).
viral infection (continued). "These host responses to this signaling cascade are documented to control bacterial and parasitic infection as well as herpesvirus reactivation, but the contribution of innate CD40 signaling during acute virus infection and the associated pathology have not been extensively studied." (PMID 37376652, 2023). "Therefore, CD38 and CD40 expression on monocytes of COBRA participants may be down regulated in response to viral infections and a high inflammatory environment." (PMID 33123168, 2020). "Both TRAIL‐R1 and 2 were upregulated by viral infection but the increase was significant especially upon TMZ‐CD40L expression induced by LOAd700 and/or LOAd703 in the cell lines expressing CD40 (T24 and PEA2)." (PMID 38494863, 2024). "CD40 activation by agonistic mouse antibody FGK4.5 has been shown to induce functional, antigen-specific immune responses in tumor models and viral infections (45, –, 48), supporting the possibility of using this approach to treat HBV." (PMID 37948314, 2023). "Stimulation of B cells with TLR ligands or by viral infection has been shown to enhance antigen presentation function by upregulating costimulatory molecules CD80, CD86, and CD40, as well as MHC molecules." (PMID 36224474, 2022). "According to previous studies other sICs, such as CD27, CD40, and T cell exhaustion makers including TIM-3 have been reported to play significant roles in immune-mediated infection control in viral infections." (PMID 36045684, 2022). "During viral infections, neutrophils express HLA-DR (MHC class II), CD80, and CD40, which contribute to antigen-specific CD4+ T-cell response." (PMID 34411088, 2021). "In cells sorted three days after viral infection with Theiler's murine encephalomyelitis virus, surface receptors (including CD45, CD11b, CD40, CD80, CD86) were upregulated in spinal microglia compared to brain microglia." (PMID 24914808, 2014). "Fas on the other hand was highly expressed by both CD40‐positive cell lines and virus infection did not further augment expression." (PMID 38494863, 2024). "Using both mouse and human systems, the thymic effects of systemic immunostimulatory regimens, such as high dose IL-2 (HD IL-2) with or without agonistic anti-CD40 mAbs and acute primary viral infection, were investigated." (PMID 39315105, 2024). "During viral encephalitis, the major group of MHC class II proteins, as well as the costimulatory molecules CD40, CD16, CD32, and CD86, are expressed on the surface of activated M1 microglia following viral infection, while M2 microglia typically express CD206 and ARG-1." (PMID 36918933, 2023). "When samples were grouped into viral vs. non-viral, EVP-associated CD40 and CD44 signals were elevated in those with virus infection (p = 0.0413 and p = 0.0176, respectively)." (PMID 37622115, 2023). "Apart from this similarity, different virus infection pathways owned their unique genes, with STAT1,RSAD2 and IRF9 in the influenza A pathway,IL-2RA,IL-2RB and CD40 in the HTLV-1 infection pathway, HCFC1, MAP3K7, SOCS3, IRF9, HMGN1, and FAS in the herpes simplex infection pathway." (PMID 35795668, 2022). "CD40, a member of the tumor necrosis factor receptor superfamily, interacts with CD40L on activated T cells and helps in immune activation during bacterial, fungal, parasitic and viral infections." (PMID 22724038, 2012). "Furthermore, CD8+ (p < 0.0001), CD2+ (p < 0.0001), CD44+ (p = 0.0176), and CD40+ (p = 0.0413) EVP signals were significantly increased in the CSF from individuals with viral infections compared to those without." (PMID 37622115, 2023). "First, there were both Ifit + and CD40+ macrophages present within the spinal cords of both PLX5622 and control mice, suggesting these cells may be responsible for host defense in response to viral infection." (PMID 32449994, 2020).
viral infection (continued). "We then sought to determine whether infection with γHV-68 AC-RTA would, in contrast to latent γHV-68 infection, not upregulate CD40 and also establish whether CD40 expression is an important key to immunological regulation during latent viral infections." (PMID 26356194, 2015). "Thus, CD40 induction in PMVECs depends on IFNγ rather than direct viral infection." (PMID 41542053, 2026). "Hepatocytes, which have strong immune inhibitory activities due to a lack of costimulatory factors, such as CD40, CD28 or ICOS, display reversed immune regulatory activities after TLR stimulation or viral infection, leading to significantly improved T-cell activation." (PMID 36224474, 2022).
multiple sclerosis (38 papers, 1998 to 2024). A progressive autoimmune disorder affecting the central nervous system resulting in demyelination. "SNP rs6074022, located in the promoter of CD40, has been shown to be associated with CD40 mRNA expression levels in whole blood from patients with multiple sclerosis (MS) and healthy controls." (PMID 34149627, 2021). "Abnormal expression of CD40 has been associated with autoimmune inflammatory diseases such as multiple sclerosis, as well as AD pathology in experimental animals." (PMID 31440141, 2019). "The multiple sclerosis risk allele rs4810485*T, associated with lower CD40 surface expression levels in the flow cytometry data, corresponded to lower IL-10 levels." (PMID 29361022, 2018). "In line with flow cytometry data, the multiple sclerosis risk allele rs4810485*T shows a trend for association with lower total CD40 expression (P = 0.057)." (PMID 29361022, 2018). "Human genetic and animal studies have implicated the costimulatory molecule CD40 in the development of multiple sclerosis (MS)." (PMID 26068105, 2015). "Macrophages/microglia have been shown to express CD40 in patients with multiple sclerosis, and CD40-deficient mice fail to develop these diseases." (PMID 25038616, 2014). "We also investigated rs1883832, whereby the common variant increases the efficiency of CD40 translation and which has been associated with Graves’ disease, multiple sclerosis, and Crohn’s disease." (PMID 21976957, 2011). "We observed highly significant associations between CD40 expression and the rs4810485 genotype in all B cell subsets (patients: P ≤ 5.10 × 10−5, controls P ≤ 4.09 × 10−6), with each copy of the multiple sclerosis risk allele rs4810485*T corresponding to lower CD40 cell surface expression levels." (PMID 29361022, 2018). "In order to study the effect of multiple sclerosis risk variants mapping within the genes for CD40 (rs4810485) and CD86 (rs9282641) on the surface expression of these co-stimulatory molecules in B cells we collected PBMCs from 68 untreated multiple sclerosis patients and 162 healthy volunteers." (PMID 29361022, 2018). "Moreover, a recent study in Russians showed the association of two CD40 variants rs6074022 and rs1883832 with multiple sclerosis (MS)—where only rs6074022 reached genome-wide significance." (PMID 25786114, 2015). "Others have reported that silencing or knock-out of CD40 in immature DC fosters strong, protective tolerance responses in mouse models of allergic disease and multiple sclerosis." (PMID 33793599, 2021). "In untreated multiple sclerosis patients, the myeloid cell subset showed a trend for decreased CD40 MFI (P = 0.0024)." (PMID 29361022, 2018). "The top SNP near CD40 (20q13.12) has been associated with IBD, CD and Kawasaki disease; this regions is associated with RA, multiple sclerosis, tonsillectomy, and chronic hepatitis B infection." (PMID 29309429, 2018). "Preclinical assessment of anti-CD40 antibody in a model of multiple sclerosis (MS) in monkeys provided additional support for the importance of CD40-CD40L interaction in autoimmune diseases." (PMID 28456914, 2017). "The consortia “anti-CD40 in multiple sclerosis,” TRIAD, and PRIMOMED were all aimed at the development of immunosuppressive therapies in non-human primate EAE and CIA models." (PMID 27872622, 2016). "CD40 has an important role in neuroinflammatory diseases and abnormal expression of CD40 and its ligand CD154 has been shown in Alzheimer's disease, multiple sclerosis, and HIV-1 associated dementia." (PMID 26388737, 2015). "In addition, our MR analysis identified a potential causal role for the CD40 pathway in IBD (including both CD and UC) and multiple sclerosis." (PMID 37563310, 2023). "Similarly, the relationship between glial cells activation status evaluated using MHC II, CD86, and CD40 with Treg levels was previously shown in animal model of multiple sclerosis before." (PMID 35571563, 2022).
multiple sclerosis (continued). "In addition, CD40-silenced immature DC have been noted to reverse the disease phenotype in mouse models of allergic rhinitis and multiple sclerosis." (PMID 33793599, 2021). "CD40/CD40L interaction has been reported to enhance the inflammatory response in multiple sclerosis, and genetic ablation or antibody-mediated inhibition of the CD40/CD40L interaction reduces the severity of experimental autoimmune encephalomyelitis (EAE), a murine model for multiple sclerosis." (PMID 30618568, 2018). "Our data in humans, however, suggest that CD40 blockade may be counter-productive in multiple sclerosis as it may inhibit beneficial mechanisms such as IL-10 producing immunomodulatory B cells." (PMID 29361022, 2018). "Similarly, functional blockade of CD40 with a murine antibody effectively prevents clinical expression in an animal model of multiple sclerosis." (PMID 29254239, 2017). "Recent association studies in multiple sclerosis (MS) have identified and replicated several single nucleotide polymorphism (SNP) susceptibility loci including CLEC16A, IL2RA, IL7R, RPL5, CD58, CD40 and chromosome 12q13–14 in addition to the well established allele HLA-DR15." (PMID 20368992, 2010). "Moreover, the functional blockade of CD40 with a murine antibody effectively prevents clinical expression in an animal model of multiple sclerosis." (PMID 20634952, 2010). "Demyelinated plaques in multiple sclerosis (MS) contain inflammatory infiltrates predominantly composed of T-cells and microglia expressing CD40L and CD40 respectively." (PMID 35456932, 2022). "For instance, different TNF receptor superfamily (TNFRSF) members and their ligands such as TWEAK/FN14 and CD40/CD40L contribute to the pathogenesis of Alzheimer’s disease and multiple sclerosis, which have a strong inflammatory component and glia involvement." (PMID 30618568, 2018). "Transitional B cells (CD19+CD24hiCD38hi) have the highest expression levels of CD40 in untreated multiple sclerosis patients, while plasmablasts (CD19+CD24−CD38hi) have the lowest CD40 MFI as well as the lowest percentage of CD40-positive cells." (PMID 29361022, 2018). "Studies in the animal model of multiple sclerosis, EAE, have shown that CD40 ablation or stimulation regulates IL-10-producing B cell number and function." (PMID 29361022, 2018). "In this study we assessed surface expression of key co-stimulatory molecules (CD40 and CD86) on B cell subtypes in patients with untreated multiple sclerosis and healthy control subjects, and correlated our findings with genotype at associated SNPs rs4810485 and rs9282641." (PMID 29361022, 2018). "In addition, immunohistological interrogation of HLA-DR+ foamy macrophages in active human multiple sclerosis lesions indicated that 70% display co-immunoreactivity for CD206 and the pro-inflammatory marker CD40." (PMID 28018179, 2016). "Hence, we additionally measured levels of total CD40 expression as well as splice-forms lacking exon 5 and/or 6 in PBMCs from the included untreated multiple sclerosis patients." (PMID 29361022, 2018).